INS (insulin)
Diseases named in the same sentence as INS in open-access papers (continued):
Sharing a sentence is not in itself a finding about the gene and the disease.
diabetes (continued). "We have confirmed that both adiponectin and HMWA are positively associated with insulin sensitivity indexes and negatively with BMI, even in our group of normoglycemic, mainly normal-weight women with no family history of diabetes." (PMID 28626772, 2017). "So far, many studies have demonstrated the efficacy of SMBG in improving decision making, obtaining better glycemic control, and facilitating a more timely and aggressive change of diabetes therapy, as well as in starting insulin therapy both in type 1 and type 2 diabetes." (PMID 29162560, 2017). "Also in this article, we will highlight the effect of insulin-mediated angiogenesis in pathological conditions such as diabetes, obesity and cancer." (PMID 28424632, 2017). "Recent advances in the expansion and directed pancreatogenic differentiation of human pluripotent stem cells (hPSCs) have intensified efforts to generate functional pancreatic islet cells, especially insulin-secreting β-cells, for cell therapies against diabetes." (PMID 28680477, 2017). "Fasting glucose and fasting insulin are glycemic traits closely related to diabetes." (PMID 28789618, 2017). "Other factors of the vegetarian diet might contribute to diabetes prevention and improved insulin sensitivity." (PMID 28613258, 2017). "The lack of data about waist circumference is a major limitation of the present analysis, especially when one considers that in the presence of diabetes, low BMI may reflect lipolysis and muscle wasting due to hyperglycemia and insufficient insulin action." (PMID 28423036, 2017). "Interestingly, individuals with Primrose syndrome develop diabetes in adulthood, which is consistent with the role of Zbtb20 in pancreatic β cells regulating glucose metabolism and insulin secretion." (PMID 28327662, 2017). "This dataset presents the relationship between pre-existing use of injectable insulin in women diagnosed with breast cancer and type 2 diabetes mellitus, the T-helper 1 and 2 produced cytokine profiles at the time of breast cancer diagnosis, and subsequent cancer outcomes." (PMID 28275667, 2017). "The family members with diabetes in this study with insulin gene variants c.17G>A, R6H were not insulin-dependent, as was observed in MG42 in this study." (PMID 28095440, 2017). "Scenario 1: Proportion of people with diabetes using insulin: 10%." (PMID 29163935, 2017). "Similarly, we determined that insulin-specific T cell responses were critical in the spontaneous mouse model of diabetes." (PMID 29259578, 2017). "Furthermore, the documented role of TRIB3 as a nexus between diabetes and cancer can inform tests of Trbl in recently developed fly insulin-regulated tumor models." (PMID 29025897, 2017). "In addition, insulin supplementation showed a significant decrease in the staining of TGFβ (0.9±0.05-fold) compared to the diabetes group." (PMID 29121074, 2017). "Insulin detemir is approved to improve glycemic control in patients with diabetes." (PMID 28720112, 2017). "The level of blood insulin in the control diabetic group was significantly lower (p < 0.001) than it was in the normal untreated mice; this result was expected, because STZ treatment to induce diabetes is known to exert toxic effects on insulin-producing β-cells." (PMID 27927080, 2017). "Insulin sensitivity, measured by the novel DISST method, was reduced in overweight women at risk of diabetes following an ad libitum high protein, high fibre diet, compared with those following a standard ad libitum high carbohydrate, low fat diet, after accounting for weight loss differences." (PMID 29186908, 2017). "However, the relationship between the further glucose-triggered insulin release and the hypoglycemic effects of released insulin has been studied rarely, which is very important for the long-term treatment of diabetes." (PMID 28772528, 2017). "Additionally, MCP-1 over-expression in insulin-producing pancreatic β cells was shown to triggered severe insulitis and diabetes." (PMID 29095944, 2017).
diabetes (continued). "Models with interaction terms revealed that the likelihood of poor overall cognitive performance was particularly high if people suffered from undiagnosed diabetes (OR = 3.44, p = 0.003) or were treated with insulin (OR = 6.19, p = 0.019) and were also inactive." (PMID 29073237, 2017). "A Pubmed search with the key words “(diabetes OR insulin OR hyperglycemia) AND (colon OR colorectal) AND cancer” was performed with no time cut-off points and further references added from the reference list of the publications found or based on the authors own experience knowledge." (PMID 28060743, 2017). "In the AG+GG genotypes, the prevalence of diabetes (8% vs 18%, age-sex-BMI-adjusted p = 0.02) and insulin plasma levels tended to be lower (4.8 vs 5.7 μU/ml, age-sex-BMI adjusted p = 0.04) whereas HDL-cholesterol levels tended to be higher (55 vs 50 mg/dl, age-sex-BMI-adjusted p = 0.04)." (PMID 29253899, 2017). "Aradigm developed the AERx® Insulin Diabetes Management System (iDMS)." (PMID 27748638, 2017). "Diabetes mellitus (DM) is the most common metabolic disorder characterized by persistent hyperglycemia, which is due to carbohydrate, protein, and lipid metabolism disturbance caused by relative or absolute deficient in insulin secretion and/or insulin action in peripheral tissues." (PMID 28567440, 2017). "Nine in-depth interviews (IDIs) and three focus group discussions (FGDs) were conducted with policymakers (n = 6), medical officers (n = 13), diabetes educators (n = 5) and a nurse, who were involved in insulin initiation management at an academic primary care clinic." (PMID 28327157, 2017). "In addition, muscle-specific knockout of PKCλ has shown to induce systemic insulin resistance and diabetes in mice, which further demonstrates the importance of aPKC in insulin-stimulated glucose transport." (PMID 28529958, 2017). "Furthermore, the T2DM miRNA signature was in full agreement with the molecular pathology of the disease since it consisted of T2DM-related pathways such as AMPK, insulin and generic diabetes signaling pathways." (PMID 28545106, 2017). "However, the study groups were similar in terms of BMI, waist circumference, physical activity, frequency of dyslipidemia, diabetes-related characteristics (insulin treatment, glycated hemoglobin, or diabetes duration), and lipid profile." (PMID 28840128, 2017). "In addition to the commonly measured insulin and blood glucose levels, the measurement of plasma lipids in patients with diabetes offers significant benefits for the prevention of cardiovascular disease, longevity, and the improvement of quality of life." (PMID 29215588, 2017). "For the reasons above, patients with preexisting diabetes on oral agents may be switched to insulin therapy in active TB once diagnosis is made, or if on insulin already; adjustments might have to be made for worsening glycemic control." (PMID 29270319, 2017). "Patients with diabetes using insulin were particularly willing to self-monitor (95.1%)." (PMID 28320330, 2017). "Hc levels were significantly increased when these rats with diabetes received insulin." (PMID 28331553, 2017). "In a subsequent report, loss of insulin secretory capacity was the primary event leading to hemochromatosis-related diabetes in thirty nonscreening patients with hemochromatosis (26 p.C282Y homozygotes) and mean SF 1501 ± 287 (standard deviation) ng/mL." (PMID 28331855, 2017). "Age, male sex, body mass index <22, diabetes in insulin therapy, prior symptomatic stroke, prior history of atrial fibrillation, dialysis, anemia, malignancy currently under treatment, LVEF below 68%, and the initial AVR strategy were associated with non-cardiac mortality." (PMID 29116212, 2017). "Diabetes mellitus is an endocrine disease of multiple aetiologies in insulin secretion." (PMID 28333074, 2017).
diabetes (continued). "Adiposity (or specific distribution of fat) rather than body weight (or BMI) may play a critical role in the regulation of insulin sensitivity and the development of diabetes." (PMID 28208657, 2017). "NLRP3- and IL-1R-deficient mice, but not ASC-deficient mice, showed reduced incidence of diabetes, less insulitis, lower hyperglycemia, and normal insulin levels compared to wild-type (WT) diabetic mice." (PMID 28289409, 2017). "Since the prevalence of diabetes is rapidly rising all over the world, the identification of nontoxic, natural compounds from a plant origin, able to mimic the insulin action, appears to be of great interest and importance, according to the last WHO expert committee recommendations." (PMID 28947927, 2017). "Importantly, disrupted insulin pulsatility has been observed in prediabetes, type 2 diabetes mellitus (T2DM), and even in normoglycaemic relatives of patients with T2DM." (PMID 29312008, 2017). "However, SDMA levels are lower in RA subjects compared to controls similarly to what occurs in diabetes mellitus and insulin-resistant patients." (PMID 28183353, 2017). "A total of 298 patients with diabetes on insulin were included for analysis." (PMID 28913365, 2017). "The insulin-loaded nanogel with prolonged and stable blood glucose reduction effect provides a possibility to use as glucose-sensitive platform for the therapy of diabetes." (PMID 28772528, 2017). "Diabetes control was optimized with increasing insulin requirements." (PMID 28606115, 2017). "Treatments followed of the diabetes mellitus type 2 include (a) increasing the amount of insulin secretion by the pancreas, (b) increasing the sensitivity of target organs to insulin, and (c) decreasing the rate at which glucose is absorbed from the gastrointestinal tract." (PMID 28878680, 2017). "Our study adds to the accumulating evidence and suggests that amylase may be an important factor in the regulation of glucose metabolism and consequently insulin secretion and thus may have an impact on obesity development and onset of diabetes." (PMID 28819193, 2017). "For the first time we detected distinguished differences in Grx expression in the islets of Langerhans in a mouse model for diabetes mellitus type 2 which could be correlated to insulin expression, cell cycle, and ROS production." (PMID 28542222, 2017). "The discovery of insulin led to a revolution in diabetes management." (PMID 28296883, 2017). "Although the mechanism causing diabetes is unclear, defects in EIF2AK3 may cause ER stress in the β-cell from misfolded proteins due to the high demand for insulin secretion, eventually leading to β-cell apoptosis." (PMID 28049534, 2017). "Men with an earlier diagnosis of diabetes had significantly lower frequencies of drug-naivety and use of oral hyperglycemic agents; and higher frequency of insulin monotherapy and combination therapy by insulin plus oral agents (p for trend values <0.001)." (PMID 29044139, 2017). "We used STZ to induce type I diabetes in mice and assessed the functioning of β-cells in STZ-mediated diabetes-induced mice by measuring body weight, water intake, blood glucose, glucose tolerance, blood serum insulin, α-amylase and various biochemical indicators." (PMID 27927080, 2017). "Two types of diabetes are discerned: type 1, or insulin-dependent diabetes, where body cannot produce insulin, generally occurs in children and young adults; type 2, noninsulin-dependent, diabetes mellitus, characterized by fasting and postprandial hyperglycaemia and relative insulin insufficiency." (PMID 32962323, 2017). "In rodent and primate models, diabetes and obesity drive overexpression of NF-κB in the hypothalamus creating a destructive feedback loop where further NF-κB expression promotes hypertension, overnutrition, and decreased insulin sensitivity." (PMID 29312321, 2017).
diabetes (continued). "In addition to insulin treatment, the durations of diabetes and BMI were found to be significant predictors for the changes in SMI in this study." (PMID 28246927, 2017). "Diabetes is a chronic metabolic disease of hyperglycemia resulting from defects in insulin secretion, action, or both: the type I diabetes (T1D) is mainly caused by beta-cell destruction and the type II diabetes (T2D) is characterized by defects in insulin action and/or secretion." (PMID 28117714, 2017). "Additionally, diabetes induced similar reductions of serum insulin levels in WT and Tg3 mice as compared with their respective controls (~82% and ~60%, respectively)." (PMID 29059224, 2017). "This may reflect the down-regulation of RE-mitochondrial interactions and tight ER-mitochondria contacts in beta cells from individuals with diabetes in comparison to controls in response to increased insulin demand." (PMID 28742858, 2017). "Because NAOs intake resulted in remarkable improvement of several indices relating to the metabolic syndrome in HFD-induced obese mice, we also tested its effects on diabetes-related indicators, such as concentrations of insulin, glucose, and adiponectin in the blood, and performed OGTT." (PMID 28333098, 2017). "The present study aimed to clarify whether sitagliptin, DPP-4 inhibitor, could regress carotid intima-media thickness (IMT) in insulin-treated patients with type 2 diabetes mellitus (T2DM)." (PMID 28250768, 2017). "Also, insulin as a pleiotropic hormone plays a pivotal role in the development of arterial hypertension and diabetes." (PMID 28464794, 2017). "As a resource for studying systemic consequences of chronic insulin insufficiency and hyperglycemia, we established a comprehensive biobank of long-term diabetic INSC94Y transgenic pigs, a model of mutant INS gene-induced diabetes of youth (MIDY), and of wild-type (WT) littermates." (PMID 28752056, 2017). "Diabetes is a chronic metabolic disorder that occurs due to insufficient pancreatic secretion of insulin (type 1 diabetes) or due to the inefficient use of the insulin by the body cells (type 2 diabetes)." (PMID 29138754, 2017). "Medication-wise, use of insulin instead of no or other diabetes medication was associated with higher odds for the low HRQoL class (OR 1.98; 95% CI 1.19–3.30; p = 0.009)." (PMID 28750026, 2017). "Fourth, glycosylated haemoglobin might be a more appropriate measurement of diabetes instead of self-reported diabetes mellitus or the use of oral antidiabetic drugs or insulin." (PMID 29084786, 2017). "Diabetes mellitus (DM) is a metabolic disorder of multiple etiologies, characterized by chronic hyperglycemia with disturbances of carbohydrate, fat, and protein metabolism resulting from defects in insulin secretion, action or both." (PMID 28683811, 2017). "Women with diabetes have a 15–20% increased risk of breast cancer compared to women without diabetes, but no impact of insulin analogue treatment has been shown." (PMID 28076434, 2017). "This could be explained by the pathophysiologic process related specifically to the presence of diabetes may involve excess circulating insulin." (PMID 29299337, 2017). "Islet transplantation could be an ideal alternative treatment to insulin therapy for type 1 diabetes Mellitus (T1DM)." (PMID 27752182, 2017). "A 5.4-year prospective cohort study among 1292 Chinese (73 diabetes cases) in Hong Kong reported an OR of 1.79 (95% CI 1.22–2.64) for the risk of diabetes with per 1 unit increment in log FGF-21 levels, after adjusting for fasting glucose, insulin, TG, HDL-C and hs-CRP." (PMID 29021814, 2017). "The data presented here is among the first to show a relationship between pre-existing use of injectable insulin in women diagnosed with breast cancer and type 2 diabetes mellitus, hematopoietic cytokine profiles at time of breast cancer diagnosis, and subsequent cancer outcomes." (PMID 28275672, 2017).
diabetes (continued). "In summary, amongst older people with diabetes who are diagnosed with CAP, risk of AKI is largely dependent on pre-existing renal function with age modifying this relationship, and prescription of insulin and/or ACE-I/ARB, as well as male sex." (PMID 28460637, 2017). "We have also identified subgroups with different trajectories of insulin sensitivity and secretion prior to the development of diabetes, suggesting important heterogeneity in the relative contributions of insulin sensitivity and secretion before diagnosis of type 2 diabetes." (PMID 28409212, 2017). "Diabetes mellitus (DM), a complex metabolic syndrome, is due to the inability of the pancreas to produce and/or secrete insulin, referred as insulin deficiency or improper insulin signal transduction by tissues like hepatic, fat, and skeletal muscle, known as insulin resistance." (PMID 28835899, 2017). "A strategy used was to seek like-minded peers, which involved searching for sufficient and relevant information that was more directed towards their particular problems related to the diabetes; for example, how to handle fluctuating blood glucose levels and insulin doses, or how to handle fatigue." (PMID 29092688, 2017). "Another prospective study done by the same group found that adding metformin to insulin regimens led to better glycemic control in patients with diabetes who undergo CABG without causing metabolic acidosis." (PMID 28558845, 2017). "Mean age at diabetes diagnoses was 52.8 years, 59.5 years for women regulating diabetes by diet, 53.6 years for women taking oral antidiabetic agents, and 41.2 years for women taking insulin." (PMID 27832382, 2017). "Although ADAMTS13 activity was positively associated with fasting glucose and insulin, the association with incident diabetes did not change when we adjusted for these covariates." (PMID 27787621, 2017). "Diabetes is a metabolic disorder which is caused by partial or complete absence of insulin or insulin resistance." (PMID 28854906, 2017). "Therefore, the transduction of insulin enhanced the synthesis of glycogen and reduced the blood glucose level, eventually reversing diabetes." (PMID 28970780, 2017). "This insulin-independent state was confirmed by response to oral antihyperglycemic drugs, metformin and glipizide, which resolved glucose intolerance and extended survival compared with guinea pigs with uncontrolled diabetes." (PMID 28093504, 2017). "Evidence from animal studies indicates that DHEA treatment could result in increased insulin-induced glucose uptake in rat models of type 2 diabetes and moderate the severity of diabetes." (PMID 27771738, 2017). "Recent genomic analysis in humans and rodents revealed that the gain of function mutation in α2A-AR, is linked to reduced insulin secretion which also occurs in absence of enhanced sensitivity and thus predisposes the development of diabetes." (PMID 28121620, 2017). "To date, several markers have been available to indicate an increased risk for the onset and progression of diabetes, such as inflammatory markers or proinsulin/insulin ratio, however they are not easily feasible for large scale screening." (PMID 28464794, 2017). "The on-off regulation of drug release offers an effective strategy for self-regulated insulin delivery in response to glucose, and the repeated on-demand drug delivery restricts the clinical application of glucose-sensitive carriers for therapy of diabetes." (PMID 28772528, 2017). "The first model, PD15 (diabetes model linking insulin, glucose and weight), was found to be at a local minimum during the SIR procedure: multiple sets of parameter vectors sampled from the covariance matrix were found to have lower OFV than the final estimates." (PMID 28887735, 2017). "The national diabetes report of the USA showed that approximately 57% of all patients in 2014 were treated with OADs alone, while approximately 15% of all patients were given a combination of insulin and OADs." (PMID 27909794, 2017).